YWHAE (tyrosine 3-monooxygenase/tryptophan 5-monooxygenase activation protein epsilon)
Diseases named in the same sentence as YWHAE in open-access papers (continued):
Sharing a sentence is not in itself a finding about the gene and the disease.
autism (6 papers, 2012 to 2024). Persistent deficits in social interaction and communication and interaction as well as a markedly restricted repertoire of activity and interest as well as repetitive patterns of behavior. "We have identified a family segregating a 17p13.3 duplication extending 329.5 kilobases by FISH and array-CGH involving the YWHAE gene, but not PAFAH1B1, affected by a mild dysmorphic phenotype with associated autism and mental retardation." (PMID 23035971, 2012).
Intellectual disability (5 papers, 2015 to 2025). "This cluster comprises of a selection of genes that have been associated previously with intellectual disability, such as YWHAE, SOS1, and MAP2K2, and several whose function makes them likely candidates for involvement in ID." (PMID 25781962, 2015). "Duplications on the 17p13.3 chromosomal region, impacting genes such as YWHAE, CRK, and PAFAH1B1, are established risk factors for various neuropsychiatric conditions, including intellectual disability, autism spectrum disorder, and behavioral problems." (PMID 40642416, 2025). "Duplications on 17p13.3 affecting YWHAE, CRK, and/or PAFAH1B1 have been identified as susceptibility factors for intellectual disability, hypotonia, autism spectrum disorders, behavioral disturbances, brain malformations, dysmorphic facial features, and limb anomalies." (PMID 40642416, 2025). "After consolidating intellectual disability gene lists from two databases and one recent review article, we identified eight LRRK2 interacting proteins that have previously been linked to intellectual disability: ACTB, ACTG1, ATRX, DYNC1H1, HERC2, PPP2R1A, TUBA1A, and YWHAE." (PMID 31963867, 2020).
Cognitive impairment (4 papers, 2017 to 2024). Abnormal cognition is characterized by deficits in thinking, reasoning, or remembering. "The abnormal expression of YWHAE at the end of the acute phase of infection suggests potential early neuronal dysfunction potentially linked to clinical and subjectively reported cognitive impairment." (PMID 38921807, 2024).
Alzheimer disease (3 papers, 2021 to 2025). A progressive, neurodegenerative disease characterized by loss of function and death of nerve cells in several areas of the brain leading to loss of cognitive function such as memory and language. "Together, they mitigate CDK5-induced neurodegeneration by regulating Tau hyperphosphorylation, oxidative stress, and neuronal apoptosis, making FAM110B and YWHAE potential therapeutic targets in Alzheimer’s disease." (PMID 40018519, 2025). "As YWHAE was originally identified in the brain, its pathological effects were initially investigated in the field of neurological diseases, such as Parkinson’s and Alzheimer’s disease, brain excitotoxic injury, and myocardial ischemia reperfusion, among others." (PMID 34107979, 2021). "Multiple 14-3-3 homologues, YWHAB, YWHAE, YWHAG and YWHAZ, were also found to be consistently upregulated in Alzheimer's disease." (PMID 40491829, 2025). "In the Deregulated CDK5 Triggers Multiple Neurodegenerative Pathways in Alzheimer’s Disease (R-HSA-8862803.4) pathway, it interacts with YWHAE (14–3-3ε), stabilizing the cytoskeleton and modulating stress responses." (PMID 40018519, 2025).
colon cancer (3 papers, 2013 to 2019). "To further explore the effects of the interaction of miR-6778-5p and YWHAE on CRC cells, we first investigated the level of YWHAE in clinical samples of human colon cancer by performing data mining in publicly available colon cancer datasets using the Oncomine platform (reporter ID: 210317_s_at)." (PMID 31438886, 2019). "Taken together, we conclude that circRNA CBL.11 may function as a competing endogenous RNA to regulate the YWHAE expression through sponging up miR-6778-5p and exert regulatory functions for colon cancer." (PMID 31773035, 2018). "Bioinformatic and luciferase reporter analyses showed that YWHAE (14-3-3e), a member of the 14-3-3 protein family, was the direct target of miR-6778-5p, which mediated the function of miR-6778-5p in proliferation of colon cancer cells through inhibiting the activation of p38 MAP kinase." (PMID 31773035, 2018). "In order to gain insight into YWHAE-mediated molecular pathways in CRC progression, gene set enrichment analysis (GSEA) in the published TCGA colon cancer database (n = 521) was performed." (PMID 31438886, 2019).
epilepsy (3 papers, 2017 to 2020). A brain disorder characterized by episodes of abnormally increased neuronal discharge resulting in transient episodes of sensory or motor neurological dysfunction, or psychic dysfunction. "The remaining group of functional proteins, including YWHAB, YWHAE, YWHAQ, and YWHAZ, that contribute to epilepsy turn out to be encoded by the so-called 14-3-3 family of proteins." (PMID 28255556, 2017). "Thus, YWHAE, CRK, and PAFAH1B1 are critical genes involved in epilepsy." (PMID 29628935, 2018). "Two patients with deletions of YWHAE and CRK, but not PAFAH1B1, were described as having macrocephaly, epilepsy, and non-specific changes in white matter, among other clinical features." (PMID 29628935, 2018).
lung carcinoma (3 papers, 2009 to 2024). "By exploring the underlying mechanism, we found that circSORBS1 regulates RUFY3 expression directly and indirectly, activates the YWHAE/BAD/BCL2 apoptosis signalling pathway, and ultimately inhibits the development of lung cancer." (PMID 38915053, 2024). "This dual regulatory mechanism leads to an increase in RUFY3 protein levels, which ultimately activates the YWHAE/BAD/BCL2 apoptotic signalling pathway and suppresses lung cancer progression." (PMID 38915053, 2024). "In summary, we elucidated that circSORBS1 activates the RUFY3/YWHAE/BAD/BCL2 signalling pathway through both a sponging mechanism and direct mRNA binding, ultimately inhibiting the development of lung cancer." (PMID 38915053, 2024). "In lung cancer, we were the first to find that RUFY3 interacts with YWHAE." (PMID 38915053, 2024).
ovarian carcinoma (3 papers, 2021 to 2023). A malignant neoplasm originating from the surface ovarian epithelium. "We demonstrated that YWHAE expression was significantly increased in ovarian cancer tissues, which was a risk factor for the prognosis of ovarian cancer." (PMID 34107979, 2021). "Altogether, this study demonstrates that YWHAE is substantially upregulated in ovarian cancer tissues, representing a risk factor for the prognosis of ovarian cancer that is positively correlated with HE4 expression." (PMID 34107979, 2021). "This suggests that high YWHAE expression may represent a risk factor for the prognosis of ovarian cancer." (PMID 34107979, 2021). "Moreover, YWHAE upregulation was associated with advanced stages of ovarian cancer and poor patient prognosis." (PMID 34107979, 2021). "Our results suggest that YWHAE could be used as a prognostic factor and may trigger new research ideas for further understanding the underlying pathogenesis and improving the diagnosis and treatment of ovarian cancer." (PMID 34107979, 2021). "Taken together, these results demonstrate that YWHAE expression can enhance the proliferation of ovarian cancer cells while also promoting cell cycle progression and inhibiting cellular apoptosis." (PMID 34107979, 2021). "The effect on ovarian cancer cell invasion and migration upon transient knockdown, or stable overexpression of YWHAE was next evaluated by transwell, and scratch experiments." (PMID 34107979, 2021). "Analysis of YWHAE expression in several ovarian cancer cell lines revealed higher levels in CAOV3 and ES2 than in OVCAR3 and A2780 lines." (PMID 34107979, 2021). "For ovarian cancer, YWHAE expression was significant in 185 ovarian carcinoma tissues compared with 10 ovarian surface epithelium tissues." (PMID 34107979, 2021). "Altogether, these results demonstrate that YWHAE promotes invasion, migration, and epithelial–mesenchymal transition of epithelial ovarian cancer cells." (PMID 34107979, 2021). "Changes in cell invasion, epithelial–mesenchymal transition, migration, proliferation, apoptosis, and cell cycle before and after differential expression of YWHAE were also explored in ovarian cancer cell lines and via in vivo experiments." (PMID 34107979, 2021). "Similarly, overexpression of YWHAZ is a prognostic biomarker for breast tumors and ovarian cancer, and a reduction in YWHAE levels has been seen in gastric carcinogenesis." (PMID 36834640, 2023). "Improved knowledge regarding the activity of YWHAE and HE4 may provide a basis to further explore the development and progression of ovarian cancer and to design novel diagnostic strategies." (PMID 34107979, 2021). "In addition, YWHAE enhanced invasion, migration, and proliferation, but inhibited the apoptosis of ovarian cancer cells." (PMID 34107979, 2021). "Through induced differential expression of YWHAE and in vivo experiments, we also demonstrated that YWHAE contributes to ovarian cancer cell invasion, epithelial–mesenchymal transition, and migration, as well as to the enhanced proliferative and anti-apoptotic responses of these cells." (PMID 34107979, 2021). "Therefore, our results suggest that YWHAE promotes the malignant biological behaviour of epithelial ovarian cancer through activation of the PI3K/AKT and MAPK pathways." (PMID 34107979, 2021). "This change in the expression profile suggests that YWHAE may be related to ovarian cancer invasion, proliferation, and drug resistance." (PMID 34107979, 2021). "Moreover, we showed for the first time that YWHAE could promote the invasion, migration, and proliferation of epithelial ovarian cancer through PI3K/AKT and MAPK pathways." (PMID 34107979, 2021). "Furthermore, YWHAE and its downstream pathways may represent new therapeutic targets for ovarian cancer." (PMID 34107979, 2021).
ovarian carcinoma (continued). "The levels of YWHAE and HE4 were evaluated in CAOV3 and ES2 ovarian cancer cell lines using cellular immunohistochemistry, revealing that both proteins were expressed in these lines, co-localising in the cytoplasm and cell membranes." (PMID 34107979, 2021). "Spearman’s correlation analysis confirmed that YWHAE and HE4 expression is positively correlated in ovarian cancer (correlation coefficient Rs = 0.277, P = 0.013)." (PMID 34107979, 2021). "In addition, recent reports indicate that YWHAE, as a HE4 interacting protein, can affect ovarian cancer malignant behavior through regulating PI3K/AKT and MAPK pathways." (PMID 35136419, 2022). "Next, the co-expression of YWHAE and HE4 was evaluated in 80 cases of ovarian cancer." (PMID 34107979, 2021).
cervical carcinoma (2 papers, 2009 to 2012). A carcinoma arising from either the exocervical squamous epithelium or the endocervical glandular epithelium. "Also, IPA diseases analysis data showed 8 proteins were associated with cervical cancer, including ANX1, ANX2, ANX 5, ENO1, HSP90AB1, YWHAE, TFRC, HSP90, and KRT19." (PMID 23243437, 2012).
liver cancer (2 papers, 2024). An epithelial or non-epithelial malignant neoplasm that arises from the liver. "We identified YWHAE as significantly associated with liver fibrosis, AVIL, FIS1, MUC1, ACOT7, CLUH, HNF4A, and TNFSF10 with liver cancer, and AVIL with liver disease-related mortality (FDR-adjusted P values < 0.05)." (PMID 38862964, 2024). "Intriguingly, we found CAPN2 protein expression was positively correlated with YWHAE protein expression in liver cancer cell lines according to CCLE database." (PMID 39739077, 2024).
lymph node metastasis (2 papers, 2021 to 2022). "Univariate and multivariate Cox regression analysis of YWHAE expression with age, pathological type, degree of differentiation, FIGO stage, and lymph node metastasis, demonstrated that YWHAE expression and FIGO staging are risk factors for the prognosis of epithelial ovarian malignancies." (PMID 34107979, 2021).
multiple myeloma (2 papers, 2021 to 2023). "In addition, CD138+ cells from four patients with relapsed refractory myeloma and PBMCs from four healthy donors were collected, and the protein levels of TRIP13, YWHAE, and p-ERK were determined by performing immunoblotting." (PMID 38012658, 2023).
osteoporosis (2 papers, 2021 to 2024). A condition of reduced bone mass, with decreased cortical thickness and a decrease in the number and size of the trabeculae of cancellous bone (but normal chemical composition), resulting in increased fracture incidence. "Also, existing research shows YWHAE is mostly related to tumor diseases; yet, its role in osteoporosis remains unclear." (PMID 38169377, 2024).
renal carcinoma (2 papers, 2011 to 2014). A carcinoma arising from the epithelium of the renal parenchyma or the renal pelvis. "Quantitative protein expression profiling revealed that overexpression of YWHAE prompt the proliferation of renal cancer cells." (PMID 24997640, 2014).
sarcoma (2 papers, 2022 to 2025). A usually aggressive malignant neoplasm of the soft tissue or bone. "Similar findings of positive TrkA IHC have also been described in BCOR and YWHAE rearranged sarcomas." (PMID 36726909, 2022). "In this study, they included CIC::DUX4, BCOR-altered, EWSR1::ATF1/CREB1, and YWHAE::NUTM2B sarcomas, as well as fusion-negative SRCSs, reflecting the expanding molecular landscape within this spectrum." (PMID 41514642, 2025).
gastric tumor (1 paper, 2016). "YWHAE immunoreactivity was observed in only 6 (4.7%) of the gastric tumor tissue samples." (PMID 27863420, 2016).
glaucoma (1 paper, 2018). Increased pressure in the eyeball due to obstruction of the outflow of aqueous humor. "These proteins included the 14-3-3 protein epsilon (YWHAE) and 14-3-3 protein zeta/delta (YWHAZ), which belong to the same protein family and YWHAZ has been previously found to be upregulated in the tears of patients using topical anti-glaucoma medication." (PMID 30104599, 2018).
heart failure (1 paper, 2026). Inability of the heart to pump blood at an adequate rate to meet tissue metabolic requirements. "Colocalisation with heart failure implicates 23 shared loci and bioinformatic analysis prioritises genes including HSPB7, CAMK2D, ALDH2, ENG, and YWHAE." (PMID 41760662, 2026).
lung adenocarcinoma (1 paper, 2021). A carcinoma that arises from the lung and is characterized by the presence of malignant glandular epithelial cells. "The ToppFun FEA, relative to diseases, predicted a possible association of the RAC1, CFH and 5 of the 14-3-3 protein family genes, namely SFN, YWHAB, YWHAE, YWHAG and YWHAZ with lung adenocarcinoma." (PMID 35366267, 2021).
macrosomia (1 paper, 2019). "Microduplications at 17p13.3, involving the YWHAE and CRK genes, similarly to our patient, are associated with macrosomia in the majority of cases." (PMID 31749829, 2019).
microcephaly (1 paper, 2015). A congenital or acquired developmental disorder in which the circumference of the head is smaller than normal for the person's age and sex. "Other genes within the combined network are involved in neuronal progenitor cell proliferation, a common mechanism underlying microcephaly (RAC1 and GNB1) and neuronal development (CEBPB, L1CAM, MAPT, PAK2, SPTBN1, and YWHAE)." (PMID 25781962, 2015).
oesophageal cancers (1 paper, 2021). "Although high expression of YWHAE has been described in colorectal, liver, kidney, breast, gastric, and oesophageal cancers, its specific mechanism of action remains unclear." (PMID 34107979, 2021).
omphalocele (1 paper, 2025). Omphalocele is an embryopathy classified in the group of abdominal celosomias and is characterized by a large hernia of the abdominal wall, centered on the umbilical cord, in which the protruding viscera are protected by a sac. "While PAFAH1B1, YWHAE and CRK are associated with major phenotypes of 17p13.3, RTN4RL1 may be involved in white matter changes and HIC1 might contribute to the occurrence of omphalocele." (PMID 40390087, 2025). "The findings of this study indicate that PAFAH1B1, YWHAE and CRK are associated with major phenotypes of 17p13.3, and RTN4RL1 may be involved in white matter changes and HIC1 might contribute to the occurrence of omphalocele." (PMID 40390087, 2025).
pervasive developmental disorder (1 paper, 2020). A category of developmental disorders characterized by impaired communication and socialization skills. "Studies have reported that individuals with duplications within YWHAE were characterised by a mild neurocognitive and pervasive developmental disorder phenotype in the presence of minor craniofacial abnormalities." (PMID 33062692, 2020).
plasma cell leukemia (1 paper, 2023). An aggressive plasma cell neoplasm characterized by the presence of neoplastic plasma cells in the peripheral blood. "Additionally, the overexpression of YWHAE and TRIP13 was determined to be associated with an advanced tumor stage, and patients with plasma cell leukemia (PCL) had higher YWHAE levels." (PMID 38012658, 2023).
preeclampsia (1 paper, 2024). Preeclampsia is a hypertensive disorder of pregnancy that is characterized by new-onset hypertension with proteinuria presenting after 20 weeks of gestation, and depending on mild or severe forms may initially present with severe headache, visual disturbances, and hyperreflexia. "Several hub genes, including ELMO1, YWHAE, and IL6ST, were significantly reduced in the placental vessels in preeclampsia." (PMID 39600942, 2024).
renal failure (1 paper, 2014). "For the rest four hub genes, SRSF1, CAND1, SMURF1, and YWHAE, no previous report of their association with renal failure has been proposed before." (PMID 24997640, 2014).
synucleinopathy (1 paper, 2017). A neurodegenerative disease that is characterized by the abnormal accumulation of aggregates of alpha-synuclein protein in neurons, nerve fibers or glial cells. "A nominally significant inverse correlation was observed for CPLX1 and a trend towards inverse correlation for YWHAE, two phenomena that we had previously identified as synucleinopathy markers in mouse mutant midbrain." (PMID 28108469, 2017).